EDEM3 (ER degradation enhancing alpha-mannosidase like protein 3)
Diseases named in the same sentence as EDEM3 in open-access papers:
EDEM3 is named in the same sentence as 25 diseases in open-access papers, as found by Europe PMC text mining. Sharing a sentence is not in itself a finding about the gene and the disease. The quoted sentences say what the papers report.
prostate carcinoma (4 papers, 2016 to 2025). A carcinoma that arises from epithelial cells of the prostate gland. "To understand why loss of EDEM3 in prostate cancer cells reduces cell survival, we performed RNA sequencing of our CWR22Rv1 shRNA stable cell line." (PMID 35897761, 2022). "Of interest, both the ‘unfolded protein response’ (FDR = 0.019) and the ‘PERK-mediated unfolded protein response’ (FDR = 0.002) were identified as altered processes following loss of EDEM3 in prostate cancer cells." (PMID 35897761, 2022). "This is consistent with our previous study, where loss of EDEM3 reduced prostate cancer cell viability." (PMID 35897761, 2022). "This strongly indicates that EDEM3 expression is associated with the UPR in prostate cancer clinical tissue." (PMID 35897761, 2022). "Here, we find that EDEM3 is upregulated in prostate cancer, and this is linked to poorer disease-free survival." (PMID 35897761, 2022). "To confirm that loss of EDEM3 results in an increase in ER stress in prostate cancer cells, we measured expression of GRP78, a common marker of ER stress." (PMID 35897761, 2022). "We previously found that loss of EDEM3 in prostate cancer cells results in a significant decrease in cellular viability." (PMID 35897761, 2022). "Reportedly, the inhibition of EDEM3 expression can reduce triglyceride levels in vivo and the radioresistance of prostate cancer cells." (PMID 39650190, 2024). "Depletion of EDEM3 from prostate cancer cells induces an ER stress transcriptomic signature, and EDEM3 overexpression is cyto-protective against ER stressors." (PMID 35897761, 2022). "The glycosylation enzyme EDEM3 is controlled by androgen signalling and is important for prostate cancer viability." (PMID 35897761, 2022). "EDEM3 expression also positively correlates with genes involved in the unfolded protein response in prostate cancer patients, and its expression can be induced through exposure to radiation." (PMID 35897761, 2022). "To interrogate the functional effect of EDEM3 in prostate cancer, we next generated stable prostate cancer cell lines with knockdown of EDEM3." (PMID 35897761, 2022). "This suggests that overexpression of EDEM3 in prostate cancer cells can lead to a reduction in ER stress and apoptosis-associated gene signatures." (PMID 35897761, 2022). "In our previous work, we identified ER Degradation Enhancing Alpha-Mannosidase Like Protein 3 (EDEM3) as an androgen-regulated gene in prostate cancer." (PMID 35897761, 2022). "Here, using in vitro functional assays and transcriptomic analysis, we identify EDEM3 as an important ERAD- and UPR-associated gene, responsible for ensuring protection from ER stress in prostate cancer cells." (PMID 35897761, 2022). "As EDEM3 is upregulated in prostate cancer tissue, we next created cell line models with overexpression of EDEM3." (PMID 35897761, 2022). "Our data thus implicate increased levels of EDEM3 with a role in prostate cancer pathology and reveal a new therapeutic opportunity to sensitise prostate tumours to radiotherapy." (PMID 35897761, 2022). "Our findings implicate increased levels of EDEM3 in prostate cancer pathology and identify a new therapeutic opportunity to sensitise prostate tumours to radiotherapy." (PMID 35897761, 2022). "To understand the role of EDEM3 in the ER stress response in prostate cancer, we treated EDEM3 overexpressing cells with the ER stressing agents thapsigargin and tunicamycin for 24 h." (PMID 35897761, 2022). "Taken together, these data show that EDEM3 is correlated with ER stress markers in prostate cancer patients, and that it is upregulated in response to ER stress in prostate cancer cells." (PMID 35897761, 2022). "Of 31 reciprocally-regulated glycosylation enzymes, a set of 8 (GALNT7, ST6GalNAc1, GCNT1, UAP1, PGM3, CSGALNACT1, ST6GAL1 and EDEM3) were significantly up-regulated in clinical prostate carcinoma." (PMID 27428423, 2016).
prostate carcinoma (continued). "This hypothesis is supported by recent studies indicating high EDEM3 levels in prostate cancer patients, conferring cyto-protection against ER stressors." (PMID 39838427, 2025). "Notably, EDEM3 overexpression induces resistance to radiotherapy in prostate cancer cells, while EDEM3 depletion triggers strong ER stress and restores cell sensitivity to treatment." (PMID 39838427, 2025). "An increase in cellular viability was observed in irradiated LNCaP and CWR22Rv1 cells with upregulated EDEM3 compared to control cells, suggesting that high levels of EDEM3 might confer radio-resistance to prostate cancer cells." (PMID 35897761, 2022). "We next tested whether EDEM3 depletion in a second prostate cancer cell line would promote similar gene expression changes in UPR and apoptosis-associated genes." (PMID 35897761, 2022). "Our data suggest that EDEM3 acts as a pro-survival factor in prostate cancer cells, and that upregulation of EDEM3 may protect cancer cells from ER stress and have implications for radio-resistance in prostate cancer cell lines." (PMID 35897761, 2022). "Future work may investigate a clinical role for EDEM3 as a therapeutic target in combination with radiotherapy for prostate cancer." (PMID 35897761, 2022). "As such, we focussed on further understanding the role of EDEM3 in prostate cancer biology." (PMID 35897761, 2022). "We tested whether levels of EDEM3 expression correlate with UPR stress sensors in prostate cancer patient tissue." (PMID 35897761, 2022). "Here, we present proof-of-concept data to show for the first time that targeting EDEM3 may provide an opportunity to reduce levels of radio-resistance, and that the role of EDEM3 as a therapeutic target for prostate cancer warrants further investigation." (PMID 35897761, 2022). "Importantly, the overexpression of EDEM3 promotes radio-resistance in prostate cancer cells and radio-resistance can be reduced through depletion of EDEM3." (PMID 35897761, 2022). "As loss of EDEM3 in our cell line models resulted in an increase in a UPR gene signature and the ER stress marker GRP78, we next investigated whether EDEM3 is associated with ER stress in prostate cancer patients." (PMID 35897761, 2022). "The data presented in this study suggest that EDEM3 is the EDEM gene which is preferentially upregulated in prostate cancer, showing consistent upregulation across 863 prostate cancer patients." (PMID 35897761, 2022).
diabetes (2 papers, 2016 to 2021). "We stained kidney cortex sections isolated from STZ- and control WT and miR-379KO mice with respective antibodies to detect EDEM3, FIS1, and TXN1 at 6 and 24 weeks after diabetes onset." (PMID 33398021, 2021). "Edem3 gene expression was significantly decreased in WT-STZ mice, but restored in miR-379KO-STZ mice, compared to their respective nondiabetic controls at 6 and 24 weeks after diabetes onset." (PMID 33398021, 2021).
diabetic kidney disease (2 papers, 2023 to 2025). Progressive kidney disorder caused by vascular damage to the glomerular capillaries, in patients with diabetes mellitus. "For example, EDEM3 was shown to be involved in diabetic kidney disease in mice, and knockout of its regulator, miR-379, alleviates negative impact of high fat diet on kidney alterations in mice." (PMID 41465472, 2025). "On the other hand, the lncRNA MGC contributes to the development of renal fibrosis in early diabetic nephropathy via the regulation of ER Degradation-Enhancing Alpha-Mannosidase-Like Protein 3 (EDEM3) expression, a molecule that is involved in the presentation of endogenous antigens." (PMID 37511572, 2023).
colon adenocarcinoma (1 paper, 2022). "Mutations of SKIDA1, CLK1, NSFL1C, OR2A5, EDEM3, and OR51V1 were associated with significant deregulation of DDX20 gene expression pattern in colon adenocarcinoma patients." (PMID 36011315, 2022).
colorectal cancer (1 paper, 2025). A primary or metastatic malignant neoplasm that affects the colon or rectum. "To understand the modified glycosylation mechanism by EDEM3, we used Pearson correlation analysis in colorectal cancers (COAD and READ) based on the TCGA databases." (PMID 39754316, 2025).
Hepatoma (1 paper, 2025). "Hepatoma cells overexpressing EDEM3 had markedly attenuated UPR signaling, but activated autophagy, as indicated by increased LC3 lipidation and autophagosome biogenesis." (PMID 39838427, 2025).
liver disease (1 paper, 2025). "Our next studies were designed to explore the mechanism of a potential association of EDEM3 levels with the development of liver disease and HBV infection, by modulating expression of the ERAD protein in HepaRG cells." (PMID 39838427, 2025).
Obesity (1 paper, 2016). Accumulation of substantial excess body fat. "Correlations of EDEM3 expression with obesity in human and mouse were also found in Nephroseq." (PMID 27686049, 2016).
prostate adenocarcinoma (1 paper, 2022). "We first looked in The Cancer Genome Atlas (TCGA) prostate adenocarcinoma (PRAD) Firehose cohort to compare EDEM1, EDEM2 and EDEM3 gene expression data in prostate adenocarcinoma tissue (n = 497) and normal prostate tissue (n = 52)." (PMID 35897761, 2022). "We treated LNCaP (prostate adenocarcinoma cells) and RWPE-1 cells (normal prostatic epithelial cells) with 10 nM synthetic androgens (R1881) for 24 h and assessed gene expression of EDEM1, EDEM2 and EDEM3." (PMID 35897761, 2022).
prostate tumour (1 paper, 2022). "This established EDEM3 as the clinically significant EDEM paralog upregulated in prostate tumours and revealed EDEM3 expression is associated with activity of the UPR pathway." (PMID 35897761, 2022). "EDEM3 expression was the only significantly upregulated EDEM gene in prostate tumour tissue compared to normal tissue (p = 0.0009)." (PMID 35897761, 2022).
renal carcinoma (1 paper, 2025). A carcinoma arising from the epithelium of the renal parenchyma or the renal pelvis. "Similarly, analysis of the Human Protein Atlas (HPA) reveals unfavourable prognoses in renal cancers overexpressing EDEM2 and EDEM3." (PMID 39838427, 2025).
thyroid cancer (1 paper, 2021). "It was also predicted that HspH3 and Grp170 interact with EDEM3, whose upregulation is linked to thyroid cancer." (PMID 33525518, 2021). "It remains to be established if the enhanced expression of EDEM3 associated with thyroid cancer is accompanied with a concomitant increase in HspH3 levels." (PMID 33525518, 2021).
type 2 diabetes (1 paper, 2026). "Many additional gene products linked to ER quality control–dependent ubiquitin-proteasomal proteolysis also show genetic evidence of linkage to human type 2 diabetes (such as EDEM3, UFD1, NPL4, BAG1, and FAF1)." (PMID 41252202, 2026).
viral infection (1 paper, 2025). "Here we propose that EDEM3 overexpression is initially part of the UPR response to an altered protein homeostasis triggered by tumorigenesis, viral infection or other cellular disorders." (PMID 39838427, 2025). "Interestingly, while the data indicated the highest EDEM3 expression in HBV-infected tissues, significantly increased EDEM3 levels were also found in normal adjacent to tumor when compared to normal tissues, irrespective of viral infection." (PMID 39838427, 2025).
cancer (6 papers, 2016 to 2025). A tumor composed of atypical neoplastic, often pleomorphic cells that invade other tissues. "And on the contrary, the depletion of EDEM3 in cancer cells induces an ER stress transcriptomic signature." (PMID 38069262, 2023). "Consistent with this, EDEM3 is induced following exposure to radiation, and high levels of EDEM3 can confer radio-resistance to cancer cells (an effect which can be reversed by targeting EDEM3)." (PMID 35897761, 2022). "Although EDEM3 had previously been identified as a vital ERAD-associated protein, its role in the UPR and ERAD in cancer had yet to be explored." (PMID 35897761, 2022). "However, EDEM3 levels were significantly higher in patients resistant to sorafenib treatment, promoting this protein as a potential new target for anti-cancer therapy." (PMID 39838427, 2025). "Having shown that in our model, EDEM3 overexpression can protect cancer cells from ER stress-inducing agents, we hypothesised that targeting EDEM3 may sensitise cancer cells to the ER stressors tunicamycin and thapsigargin." (PMID 35897761, 2022). "This is in line with our previous work suggesting that EDEM3 promotes cancer cell viability." (PMID 35897761, 2022). "As we have shown EDEM3 to be a cyto-protective against ER stressors, we suggest that targeting of EDEM3, shown here through gene knockdown, may be an effective strategy to sensitise cancer cells to ER stress-inducing agents." (PMID 35897761, 2022). "The strategy could serve as a powerful tool against EDEM3‐induced ICI‐resistant CRC cancer, highlighting the urgency and relevance of our research in the pursuit of innovative cancer treatments." (PMID 39754316, 2025). "Thus, our analysis suggests that high EDEM3 expression may be triggered at early HCC stages, when liver damage is associated with chronic exposure to risk factors such as HBV, and is sustained regardless of the cancer progression." (PMID 39838427, 2025).
tumor (3 papers, 2024 to 2025). "Specifically, we revealed that the less‐SPP1+ Mph and APOE+ Mph cells in patients with low EDEM3‐expressed tumours was associated with the best response." (PMID 39754316, 2025). "Then, we obtained in vivo evidence showing EDEM3 expression in CRC tumour cells associated with CAF infiltration, using a single‐cell RNA sequencing database." (PMID 39754316, 2025). "Analysis of publically available transcriptomic data sets confirmed the high EDEM3 expression in independent HCC patient cohorts, associated with tumor progression, poor survival prognosis and resistance to therapy." (PMID 39838427, 2025). "The tumours in the EDEM3‐overexpression group were larger in both volume and weight compared to the EV group following IgG treatment." (PMID 39754316, 2025). "Consistent with our finding, we verified that the tumours with upregulated EDEM3 have a poorer response to PD‐1 blockade therapy." (PMID 39754316, 2025). "Investigation of published transcriptomic data sets confirmed EDEM3 upregulation in independent HCC patient cohorts, associated with tumor progression, poor survival prognosis and resistance to therapy." (PMID 39838427, 2025). "Collectively, these data suggest that EDEM3 confers resistance to PD‐1 blockade by promoting macrophage migration and M2‐like polarisation, further enhancing tumour cell survival by suppressing immune responses by CD8+ T cells." (PMID 39754316, 2025). "This suggested that EDEM3 is involved in tumour immunity during progression, supported by a significant correlation between EDEM3 expression and poor prognosis in the CD8+ T‐cell‐enriched population." (PMID 39754316, 2025). "Coculturing of activated cells (Co‐PBMCs+) and EDEM3 knockdown DLD1 cells also promoted a modest increase in tumour cell killing." (PMID 39754316, 2025). "The amount of EDEM3 transcripts was significantly increased in tumor samples; the results were further confirmed at protein levels in 6 paired tissues by western blot analysis." (PMID 39838427, 2025). "We next examined the effect of EDEM3 on tumour growth and the therapeutic efficacy of PD‐1 blockade in vivo." (PMID 39754316, 2025). "The upregulated EDEM3 expression in normal adjacent to tumor compared to normal tissues suggests that the ERAD factor may also contribute to HCC development." (PMID 39838427, 2025). "Additionally, sections were stained for Ki67, a proliferation marker, revealing that tumour cells with lower EDEM3 expression post treatment with FMD+2‐DG+anti‐PD‐L1 were rarely Ki67‐positive." (PMID 39754316, 2025). "To evaluate whether EDEM3 could direct tumour immune escape and affect tumour growth, we compared the growth of EDEM3EV and EDEMOE tumours in BALB/c mice." (PMID 39754316, 2025). "Furthermore, TIMER2.0 analysis revealed the substantial infiltration of M2 macrophages in EDEM3 high‐expression CRC tumours." (PMID 39754316, 2025). "Then, we asked whether high‐EDEM3 expression in tumour cells would affect the response to immunotherapy by analysing CRC patient responses to the PD‐1 antibody using the Gene Expression Omnibus (GSE236581)." (PMID 39754316, 2025). "Additionally, high‐EDEM3 expression predominantly recruits M2‐like macrophages, creating a barrier‐protective tumour microenvironment that underpins PD‐1/PD‐L1 blockade resistance in vivo." (PMID 39754316, 2025). "To investigate this hypothesis, we evaluated EDEM3 expression in 50 tumor and 50 paired-normal adjacent to tumor liver tissues from our cohort of HCC patients." (PMID 39838427, 2025). "Besides, the subgroup analysis indicated that EDEM3 expression slightly increased according to the tumor grades, except for the undifferentiated grade IV, likely an effect of the small sample size (n = 12) available for this group." (PMID 39838427, 2025). "Indeed, our data suggest that the elevated EDEM3 expression in tumor tissues could be part of such an adaptive mechanism." (PMID 39838427, 2025).
tumor (continued). "Additionally, EDEM3 plays a role in tumour immunityduring tumour progression." (PMID 39754316, 2025). "We found that the EDEM3 expression in epithelial cells (marked by KRT18, EPCAM, KRT8) was significantly higher in tumour tissues with a large proportion of CAFs (marked by COL1A1, COL1A2, COL6A1, COL6A2) in the GSE188711 CRC dataset." (PMID 39754316, 2025). "By flagging the glycoproteins destined for degradation, EDEM3 increases the proteasomal flux and alleviates the UPR, protecting HBV-infected and tumor cells from ER stress-induced apoptosis." (PMID 39838427, 2025). "Finally, we examined the expression levels of EDEM3, CD8+ T cells, M2‐like TAMs and CAFs in human CRC tumour samples." (PMID 39754316, 2025). "Although not statistically significant, we observed a trend towards EDEM3‐overexpressed being involved in tumour promotion after control IgG treatment." (PMID 39754316, 2025). "In addition, EDEM3 overexpression in CT26 tumour cells did not significantly inhibit tumour growth in the presence of the PD‐L1 antibody treatment, likely because the basal PD‐L1 expression was already high." (PMID 39754316, 2025). "To determine whether the HBV infection-EDEM3 relationship can be validated in more relevant clinical samples, we quantified the EDEM3 mRNA in tissues from our cohort of patients, including 10 normal, 25 HBV-infected (+) and 25 uninfected (−) normal adjacent to tumor HCC livers." (PMID 39838427, 2025). "Patients #5, #6, and #7 (without tumor samples) showed an overlap of four genes (SORL1, PTPRC, MIR6819, and NAMPT), while #6 and #7 also shared five genes (CELF2, EDEM3, SMCHD1, RAVER1, and CXCR1)." (PMID 39001407, 2024).
infection (2 papers, 2025 to 2026). The state of being infected such as from the introduction of a foreign agent such as serum, vaccine, antigenic substance or organism. "Integration with RNA-seq data revealed key genes (IL1R2, RBM34, EDEM3, and MZB1) potentially critical in early infection." (PMID 42087228, 2026).
EDEM3 also shares sentences with these, for which no sentence is quoted: chronic kidney disease (1 paper); colon cancer (1); ER Stress (1); Hepatic steatosis (1); hypertensive nephropathy (1); IgA nephropathy (1); kidney diseases (1); renal fibrosis (1).